SAA2 (serum amyloid A2)
Diseases named in the same sentence as SAA2 in open-access papers (continued):
Sharing a sentence is not in itself a finding about the gene and the disease.
diabetes (4 papers, 2016 to 2022). "CD99, CLU, CD14, and SAA2 have been reported to be associated with diabetes from human serum proteins." (PMID 33995275, 2021). "Expression of transcription factors (ANGPTL2, HP, LEP, SAA1, SAA2), genes related to inflammation (SAA1, LEP), diabetes (IGFBP5) and cancer risk (SAA2) were also elevated upon exposure to 5 nM PhIP.." (PMID 27547236, 2016). "However, we did find that PhIP induces changes in gene expression in various genes that are related to inflammation (SAA1, LEP), diabetes (IBP5) and cancer risk (SAA2)." (PMID 27547236, 2016). "However, they are related to diabetes or insulin secretion (rs757110 in ABCC8, rs5215 and rs5219 in KCNJ11), carotid intima media thickness (rs2468844 in SAA2), and oligospermia (rs11703684 in PIWIL3)." (PMID 27900359, 2016). "Additionally, comparison of the expression level of LAMA2, MLL4, PLXDC2, CD14, CLU, CD99 and SAA2 in sera of healthy volunteers and patients with stroke and pre-diabetes suggests that LAMA2, MLL4 and PLXDC2 have better specificity for (pre-)diabetes than CD14, CLU, CD99 and SAA2." (PMID 33995275, 2021).
AA amyloidosis (3 papers, 2022 to 2025). Secondary amyloidosis is a form of amyloidosis, that complicates chronic inflammatory disorders (mainly rheumatoid arthritis) and is characterized by the aggregation and deposition of amyloid fibrils composed of serum amyloid A protein, an acute phase reactant. "In Caucasians, polymorphisms in the SAA1 and SAA2 (serum amyloid A1 and A2) genes have been implicated in the pathogenesis of AA amyloidosis in individuals with FFM." (PMID 36197414, 2022). "SAA1 and SAA2 are both acute-phase proteins and associated with AA amyloidosis." (PMID 38568326, 2024). "SAA1 and SAA2 are acute-phase proteins that increase during inflammation (i.e., acute-phase SAA) and contribute to AA amyloidosis." (PMID 40003925, 2025).
atherosclerosis (3 papers, 2021 to 2024). A disease characterized by the build-up of fatty material and calcium deposition in the arterial wall resulting in partial or complete occlusion of the arterial lumen. "Interestingly, Saa1 and Saa2, acute phase proteins proposed to play causal roles in atherosclerosis and AAAs, were two of the most highly downregulated proteins within AAAs from RXP470.1-treated Apoe−/− mice." (PMID 38891996, 2024). "High levels of SAA2 are relevant to chronic inflammatory diseases including atherosclerosis, rheumatoid arthritis, Alzheimer’s disease and Crohn’s disease." (PMID 34331328, 2021). "A subsequent study in Apoe-deficient male mice also lacking Saa1 and Saa2 using Saa3 suppression with an anti-sense oligonucleotide showed significantly reduced atherosclerosis." (PMID 37396595, 2023).
Insulin resistance (3 papers, 2020 to 2022). Increased resistance towards insulin, that is, diminished effectiveness of insulin in reducing blood glucose levels. "Similarly, SAA2 was also shown to be a marker of insulin resistance in mice." (PMID 33995275, 2021). "Scheja and colleagues investigated this hypothesis and found that in insulin resistance prone mice that were fed a high-fat diet, liver SAA1 and SAA2 mRNA levels, and adipose tissue SAA3 mRNA levels were increased." (PMID 35883605, 2022).
viral infections (3 papers, 2020 to 2024). "SAA2 is a useful inflammatory marker in acute viral infections such as influenza, but its decreased expression in our analysis is consistent with the aberrant inflammatory response of SARS-CoV-2 infection." (PMID 33521069, 2020). "Among these proteins, CRP, SAA1, and SAA2 are described as common markers for inflammation and combined monitoring of CRP and serum amyloid A has previously been shown to increase specificity for monitoring viral infections." (PMID 39441646, 2024). "In addition, we observed the uniqueness of the SAA2 gene expression in SARS-CoV-2 infection compared to SARS-CoV, MERS-CoV, EBOV, and H1N1 viral infections." (PMID 33301474, 2020).
Alzheimer disease (2 papers, 2021 to 2024). A progressive, neurodegenerative disease characterized by loss of function and death of nerve cells in several areas of the brain leading to loss of cognitive function such as memory and language. "Studies have demonstrated that SAA2 is associated with several chronic inflammatory diseases, including Alzheimer’s disease." (PMID 39640846, 2024).
Arthritis (2 papers, 2017 to 2024). Inflammation of a joint. "Here, we identified that Saa1, Saa2, and Saa3 expression in the liver, an extraarticular organ, were markedly increased in IL-1β–induced arthritis." (PMID 38426494, 2024). "Elimination of microbiota after the onset of arthritis resulted in suppression of intestinal SAA1, SAA2 and IL-22 expression and a specific reduction of LP Th17 cells accompanied with reduced Th17 cell abundance in joint-draining lymph nodes of the CIA mice." (PMID 29142301, 2017).
influenza (2 papers, 2020 to 2026). An acute viral infection of the respiratory tract, occurring in isolated cases, in epidemics, or in pandemics; it is caused by serologically different strains of viruses (influenzaviruses) designated A, B, and C, has a 3-day incubation period, and usually lasts for 3 to 10 days. "We actively searched for differential proteins and identified SAA2 as a potentially key diagnostic clinical marker following influenza infection." (PMID 40158620, 2026). "•SAA2 as an auxiliary diagnostic marker for influenza infection." (PMID 40158620, 2026). "Finally, we used the ELISA method to confirm that SAA2 protein can be used as an auxiliary diagnostic indicator for influenza infection." (PMID 40158620, 2026). "Preliminary results showed that SAA2 is an important molecular marker specific to influenza infection." (PMID 40158620, 2026). "The results showed that in influenza, high expression of SERPINA3, SAA1, and SAA2 was associated with a higher risk." (PMID 40158620, 2026). "In influenza, high expression of SERPINA3, SAA1, and SAA2 is associated with higher risk." (PMID 40158620, 2026). "Our study found that SAA2 increases significantly during influenza." (PMID 40158620, 2026). "Preliminary results identified SAA2 as a specific molecular marker for influenza infection." (PMID 40158620, 2026). "Our study found that SAA2 is also derived from monocytes in influenza patients." (PMID 40158620, 2026).
liver cancer (2 papers, 2023 to 2025). An epithelial or non-epithelial malignant neoplasm that arises from the liver. "Macrophage recruitment and M2 polarization was also observed in the study of the “invasive zone” of liver cancer in which a subpopulation of damaged hepatocytes produces excessive SAA1 and SAA2 for local immunosuppression in human patients." (PMID 39940756, 2025).
liver disease (2 papers, 2023 to 2025). "In metabolic-associated steatotic liver disease models, deficiency of Saa1/Saa2 in mice due to genetic KO or shRNA knockdown ameliorates steatohepatitis, suggesting that SAA is pathogenic in high-fat diet–induced liver disease." (PMID 39969482, 2025). "In addition, many novel liver disease biomarkers were discovered, such as EGF-containing fibulin-like extracellular matrix protein 1 (EFEMP1), SAA2, CPN2, ANPEP, TGFBI, and FGG." (PMID 37209815, 2023).
lung adenocarcinoma (2 papers, 2014 to 2021). A carcinoma that arises from the lung and is characterized by the presence of malignant glandular epithelial cells. "In their turn, the pro-inflammatory cytokines, IL-1β, IL-6 and TNF-α, regulators of SAA1 and SAA2 genes, were also found to be increased in patients with lung adenocarcinoma." (PMID 28250368, 2014).
adenoma (1 paper, 2023). A neoplasm arising from the epithelium. "Six genes (SAA2, SAA1, CRP, SAA3P, PLA2G2A, and APOA4) listed in the heat map also indicated that the expression of PLA2G2A was limited to the adenoma tissue, following the violin plot results." (PMID 38201587, 2023).
B-cell lymphoma (1 paper, 2023). "Although marginally significant (p = 0.053) in the discovery cohort, SAA2 was selected due to its function as an indicator of special humoral immune responses in B-cell lymphoma induced by germinal center–associated lymphoma (HGAL) genes." (PMID 37500057, 2023).
bacterial sepsis (1 paper, 2025). "SAA-/- mice carrying a deletion of the Saa1, Saa2, Saa3, and Saa4 serum amyloid A genes have better survival rates in sterile sepsis but are more prone to bacterial sepsis than their SAA+/+ counterparts, emphasizing their dual functionality in immune regulation." (PMID 40061939, 2025).
brucellosis (1 paper, 2024). Brucellosis is a bacterial infection that spreads from animals to people via unpasteurized dairy products or by exposure to contaminated animal products or infected animals. "This suggests that CRP and SAA2 may hold diagnostic value in monitoring the progression of Brucellosis to chronic infection." (PMID 39872944, 2024). "In this study, we found that in patients with chronic Brucellosis, the levels of SAA2 were elevated compared to SAA1, while the expression levels of SAA1 during the chronic phase were comparable to those of healthy individuals." (PMID 39872944, 2024). "Notably, P02741 (CRP) and P0DJI9 (SAA2) showed differential expression across all three groups, while P0DJI98 (SAA1) did not exhibit differential expression between the chronic Brucellosis group and the healthy controls." (PMID 39872944, 2024).
dysplasia (1 paper, 2020). A usually neoplastic transformation of the cell, associated with altered architectural tissue patterns. "Based on global transcriptomics by RNA sequencing, OLK with dysplasia is different from OLK without dysplasia in terms of its molecular pathology: at least 47 genes were found to be differentially expressed between OLK with and without dysplasia, including SAA1, SAA2, and KRT31." (PMID 33327496, 2020).
endometriosis (1 paper, 2025). The growth of functional endometrial tissue in anatomic sites outside the uterine body. "Meanwhile, our study suggested that higher levels of EPHB4, RSPO3, FSHB, and SEZ6L2 were associated with an increased risk of endometriosis, while lower levels of CD109, SAA1, and SAA2 were also associated with an increased risk of endometriosis." (PMID 40450304, 2025). "The results of our study indicate that a low expression of SAA1 and SAA2 is associated with an increased risk of endometriosis." (PMID 40450304, 2025). "This study indicates that the druggable genes EPHB4, CD109, SAA1, SAA2, FSHB, and SEZ6L2 may be associated with the pathogenesis of endometriosis and are potential therapeutic targets for drug treatment." (PMID 40450304, 2025). "CD109, SAA1, SAA2, FSHB, and SEZ6L2 are weakly associated with endometriosis, with higher levels of FSHB and SEZ6L2 correlating with an increased risk of endometriosis, and higher levels of CD109, SAA1, and SAA2 correlating with a decreased risk of endometriosis (PFDR < 0.05, PPH4 < 0.6)." (PMID 40450304, 2025). "We found that the druggable genes EPHB4, CD109, SAA1, SAA2, FSHB, and SEZ6L2 may be associated with the pathogenesis of endometriosis and are potential therapeutic targets for drug treatment." (PMID 40450304, 2025). "CD109, SAA1, SAA2, FSHB, and SEZ6L2 are considered to provide low-level evidence of colocalization with endometriosis (PPH4 ≤ 0.6)." (PMID 40450304, 2025).
enteritis (1 paper, 2022). Inflammation of the small intestine. "This study primarily focuses on the role of SAA1 in enteritis, and the expression levels of the subtypes SAA2-4 were also examined." (PMID 35303008, 2022).
Fever (1 paper, 2024). Body temperature elevated above the normal range. "Furthermore, the FN‐category correlated with inflammation‐related proteins such as CRP (R = 0.44), SAA1 (R = 0.44), and SAA2 (R = 0.40), and their levels were indeed increased in samples obtained from patients with mild‐FN and complicated‐FN compared to non‐fever patient samples." (PMID 39441646, 2024). "Furthermore, we found that fever‐cause categories showed the strongest correlation with PIGR (R = 0.47), SAA1 (R = 0.46), and SAA2 (R = 0.42), although no distinct pattern was discernible for fever‐cause." (PMID 39441646, 2024).
glaucoma (1 paper, 2018). Increased pressure in the eyeball due to obstruction of the outflow of aqueous humor. "Here, the expression of SAA2 was increased in TM tissues from donors with glaucoma." (PMID 29675026, 2018).
Hepatic steatosis (1 paper, 2022). Steatosis is a term used to denote lipid accumulation within hepatocytes. "TXNDC5, as we hypothesized, was correlated with hepatic steatosis and redox control in the liver, showing an increased liver mass with a higher fat content linked to Saa1 and Saa2 expressions." (PMID 35327511, 2022).
Hepatitis (1 paper, 2013). Inflammation of the liver. "In our data the SAA-1 and SAA-2 were indentified to increase with the highest degree, which is also supported that SAA has a high correlation with hepatitis." (PMID 23763817, 2013).
inflammatory bowel disease (1 paper, 2025). A spectrum of small and large bowel inflammatory diseases of unknown etiology. "In a series of studies conducted by Littman and coworkers, Saa1/Saa2 was shown to play a pivotal role in Th17 immunity using mouse models of inflammatory bowel disease and the colonization of segmented filamentous bacteria (SFB)." (PMID 39940756, 2025).
inflammatory skin disease (1 paper, 2019). Inflammatory skin disorders covers a broad category that includes many conditions ranging in severity, from mild itching to grave medical health complications These disorders are common in people of all ages and races. "SAA1 and SAA2 (another member of SAA family) contribute to inflammatory skin diseases such as acne." (PMID 31281837, 2019).
invasive ductal carcinoma (1 paper, 2024). "High concentrations of SAA2 are associated with a survival time of less than one year in women with invasive ductal carcinoma, making it a useful marker for BC recurrence." (PMID 39195217, 2024).
liver fibrosis (1 paper, 2022). "Although we noticed an upregulation of select acute phase response (e.g., Saa1, Saa2, and Orm2) and fibrosis genes (e.g., Col1a1 and Timp1) in livers of IXA4-treated DIO mice, IXA4 treatment did not increase liver fibrosis or the levels of multiple plasma cytokines." (PMID 35105890, 2022).
malaria (1 paper, 2025). Malaria is a serious and sometimes fatal disease caused by a parasite that commonly infects a certain type of mosquito which feeds on humans. "In contrast to Saa1 and Saa2, the genes Saa3 and Saa4 displayed significantly lower constitutive expressions of about 90 and 178, respectively, and their malaria-responsive expression profiles responded to vaccination, though differently." (PMID 40243929, 2025).
metabolic syndrome (1 paper, 2013). A cluster of metabolic risk factors for CARDIOVASCULAR DISEASES and TYPE 2 DIABETES MELLITUS. "Interestingly, the expression of some of these genes (C1S, SAA2, ALCAM, CTSB, YKL-40 and tenomodulin) was found to be associated with some relevant metabolic syndrome features." (PMID 23975165, 2013).
non-small cell lung carcinoma (1 paper, 2023). A group of at least three distinct histological types of lung cancer, including non-small cell squamous cell carcinoma, adenocarcinoma, and large cell carcinoma. "SAA2 expression was positively linked to the disease stage of non-small cell lung cancer." (PMID 36741315, 2023).
osteoporosis (1 paper, 2024). A condition of reduced bone mass, with decreased cortical thickness and a decrease in the number and size of the trabeculae of cancellous bone (but normal chemical composition), resulting in increased fracture incidence. "The significance of SAA2 downregulation needs to be further studied due to lack of sufficient information regarding this gene and its relationship to osteoporosis." (PMID 39497989, 2024).
ovarian tumor (1 paper, 2020). "Firstly, we examined the expression of SAA-1, SAA-2, and SAA-4 in ovarian tumor tissues and OVCAR-3 cells." (PMID 32517794, 2020). "We found that SAA-1 and SAA-4 could be expressed in ovarian tumor tissues and OVCAR-3 cell, but SAA-2 could not." (PMID 32517794, 2020).
periodontitis (1 paper, 2023). An acute or chronic inflammatory process that affects the tissues that surround and support the teeth. "Out of the 20 most upregulated genes in periodontitis tissues compared to controls, five were induced in DAC-treated GFs in our experiments (CSF3, GLDC, SAA1, SAA2, GDF15), highlighting the notion that DNMT inhibitors upregulate several genes that are associated with periodontitis pathology." (PMID 36776856, 2023).
primary immunodeficiency (1 paper, 2024). "Through correlation analysis, we found that SAA2 might be involved in classic signals involving in cancer progression, including cytokine and receptor interaction, primary immunodeficiency, drug metabolism, IL6-JAK-STAT3, E2F, and the G2M checkpoint." (PMID 39457484, 2024).
renal cell carcinoma (1 paper, 2023). "It is reported that SAA2 is significantly increased when renal cell carcinoma (RCC) patients have the highest Fuhrman grade." (PMID 37430202, 2023).
skin infection (1 paper, 2025). An inflammatory process affecting the skin, caused by bacteria, viruses, parasites, or fungi. "In a study of skin infection by S. aureus, recombinant human SAA1 and SAA2 and mouse Saa1, Saa2 and Saa3 all bind bacterial membrane and exhibit a stronger bactericidal effect in lower pH conditions." (PMID 39940756, 2025).
steatosis (1 paper, 2021). Increased lipid within the cytoplasm of cells. "Four genes had lower expression in steatosis (ABCA1, MTR, MTHFR, and PLG) and five genes had higher expression (SEPHS2, DIO1, HBB, SAA1, and SAA2) in the “selenoprotein micronutrient network” pathway." (PMID 34869521, 2021).
Stroke (1 paper, 2021). Sudden impairment of blood flow to a part of the brain due to occlusion or rupture of an artery to the brain. "LAMA2, MLL4 and PLXDC2 are specifically expressed in (pre-)diabetic sera; CD99 is expressed in the sera of both healthy and (pre-)diabetic patients; and CD14, CLU and SAA2 are expressed in the sera of healthy, (pre-)diabetic and stroke subjects." (PMID 33995275, 2021). "However, we found that CD14, CLU and SAA2 were expressed in the sera of stroke patients at various levels." (PMID 33995275, 2021).
triple-negative breast carcinoma (1 paper, 2024). An invasive breast carcinoma which is negative for expression of estrogen receptor (ER), progesterone receptor (PR), and human epidermal growth factor receptor 2 (HER2). "This study explores the role of SAA1 and SAA2 (SAA1/2) in triple-negative breast cancer using a mouse model." (PMID 39336082, 2024). "Therefore, we investigated the role of systemic SAA1 and SAA2 (SAA1/2) in a triple-negative breast cancer mouse model." (PMID 39336082, 2024). "The aim of this study was therefore to investigate the effects of SAA1/2 in an in vivo triple negative breast cancer model (TNBC), in mice lacking both SAA1 and SAA2." (PMID 39336082, 2024).
ulcerative colitis (1 paper, 2016). An inflammatory bowel disease involving the mucosal surface of the large intestine and rectum. "Four (80%) of the associated genes with these CpG sites have been linked to either ulcerative colitis (IL4R and SAA1) or CRC (LAT2 and SAA2)." (PMID 27006956, 2016).